EPO (erythropoietin)
Diseases named in the same sentence as EPO in open-access papers (continued):
Sharing a sentence is not in itself a finding about the gene and the disease.
tumor (continued). "A key aspect of our studies is the direct, serial and simultaneous visualization and assessment of both implanted tumor cells and host blood vessels to show that endogenous erythropoietin is a critical factor involved in the attraction of new capillaries to vascularize the expanding tumor mass." (PMID 17579721, 2007). "Suppression of tumor angiogenesis and growth by EPO blockade suggests that EPO may constitute a potential target for the therapeutic modulation of angiogenesis in cancer that warrants further investigation." (PMID 17579721, 2007). "In the present study, we investigated the role of EPO in tumor angiogenesis and progression." (PMID 17579721, 2007). "This study also provides the rationale to test the hypothesis whether improving tumour oxygenation by raising haemoglobin concentrations, for example, with erythropoietin in patients with TGCTs receiving chemotherapy may improve the outcome." (PMID 14647149, 2003). "EPO has been identified as a negative prognostic marker in human liver and renal cancers, where its expression is induced by hypoxic conditions associated with tumor growth and severe tumor-induced anemia." (PMID 41602576, 2026). "EPO may contribute to immunosuppression within the tumor microenvironment." (PMID 41375075, 2025). "A chronic cancer-related anemic microenvironment may foster toxic increased expression of messenger RNAs for erythropoietin protein or receptor, which in turn may lead to faster tumor growth, enhanced angiogenesis, and faster lymph node spread, ultimately resulting in tumor recurrence." (PMID 38337488, 2024). "Additionally, it plays a significant role in tumor progression and chemotherapy resistance by regulating a variety of angiogenic factors, including angiopoietin 1 and angiopoietin 2, matrix metalloproteinase, and erythropoietin, along with energy pathways." (PMID 38542288, 2024). "Consequently, it could be hypothesized that a drop in hematocrit could be an indicator of the arrest of EPO tumor production and thus of surgical success." (PMID 38610939, 2024). "In a mouse tumor-bearing model, hemoglobin concentration and hematocrit gradually decrease as the tumor progresses, and the hypoxic environment and tumor-induced anemia increase blood EPO concentration, accompanied by the aggregation of CECs in the spleen and liver other than in the bone marrow." (PMID 38045690, 2023). "At present, clinical wound treatment primarily relies on growth factor drugs such as VEGF and erythropoietin, which have high production, storage, and transportation costs and may exhibit tumor promoting effects with continuous use, and thus fail to achieve ideal therapeutic effects." (PMID 37377928, 2023). "EPO, acting through the canonical EPO-R or through ephrin-type B receptor 4 (EphB4), an alternative EPO-R, may account for the increased tumor growth and progression through downstream activation of the Src-STAT3 pathway seen in cancer patients treated with ESAs." (PMID 37543610, 2023). "Increased production of hormones physiologic for adult animals (e.g., adrenocorticotropin, norepinephrine, and erythropoietin) or typical for the foetal phase (alpha‐fetoprotein, anti‐Müllerian hormone, and parathyroid‐hormone‐related protein) might aid in tumour diagnostics." (PMID 36495211, 2023). "The erythropoietin it encodes is an erythropoietic growth factor, which can not only stimulate angiogenesis but also stimulate the proliferation of tumor cells." (PMID 35222525, 2022). "Alternatively, EPO may affect vascular endothelial cells and promote tumor angiogenesis." (PMID 35694408, 2022). "Thus, EPO and red lineage cells are new players in tumor–host interactions." (PMID 36567722, 2022). "Thus, the DCK and EPO from IRGs may regulate the expression of some specific immune checkpoints and promote the tumor escape mechanisms in HCC." (PMID 34021184, 2021).
tumor (continued). "Some studies have shown that Cistanche deserticola can increase the expression of erythropoietin and receptor mRNA, promote the proliferation of bone marrow hematopoietic stem cells, improve bone marrow suppression, and induce apoptosis of tumor cells through mitochondrial dependent pathway." (PMID 32372960, 2020). "Furthermore, EPO treatment enhances the circulating levels of angiogenic cytokines, contributing to the progression of neovascularization in tumours, and as a consequence, increased neoplasm growth." (PMID 31683939, 2019). "Secondary absolute erythrocytosis is a result of EPO overproduction, which may be appropriate as compensation to systemic hypoxia, or inappropriate in cases of EPO secreting tumours or as part of a paraneoplastic syndrome (Lording 2008; Randolph, Peterson & Stokol 2010)." (PMID 31038324, 2019). "Additionally, it was also hypothesized that the higher mortality was dependent on EPO ability to stimulate tumor growth." (PMID 30294279, 2018). "Importantly, we found that EPO expression in the tumour context correlated with pCR." (PMID 29108271, 2017). "Furthermore, systemic treatment of EPO increased infiltration of CD11b+ macrophages in tumor-draining lymph nodes and also increased VEGF-C expression in lymph-node-derived CD11b+ macrophages as well as in bone-marrow-derived macrophages in a dose- and time-dependent manner." (PMID 28703764, 2017). "Finally, we characterized the role of EPO/EPOR in hypoxia induced tumor progression." (PMID 29137269, 2017). "Recent clinical trials suggest that EPO may accelerate tumor progression and increase mortality." (PMID 28415825, 2017). "In addition, plasma from the tumor cells was also EPO-positive." (PMID 28877745, 2017). "However, systematic administration of rhEPO in xenograft mice to address tumorigenic effect of endogenous EPO is inappropriate because that may confound its pro-tumor effects by other affected organs and systems such as hematopoietic and immune systems." (PMID 29137269, 2017). "Therefore, erythropoietin supplementation in RMS patients may have the unwanted side effect of stimulating tumor progression." (PMID 27510263, 2016). "We examined if ESA exposure could activate signaling pathways by treating viable primary human tumor cell isolates with recombinant human erythropoietin (rHuEpo) and analyzing the effect on the activation state of multiple signaling proteins downstream of cell-surface receptors." (PMID 25807104, 2015). "Among them, erythropoietin (EPO) may stimulate EMT in RCC via the PI3K/Akt/mTOR pathway in agreement with the observations that the mTOR inhibitor Everolimus was able to slow down RCC tumor growth and to reverse EMT phenotype in a mouse xenograft model." (PMID 26579493, 2015). "Furthermore, systemic treatment of EPO increased infiltration of CD11b(+) macrophages in tumor-draining lymph nodes and increased VEGF-C expression in lymph node-derived CD11b(+) macrophages, as well as in bone marrow-derived macrophages in a dose- and time-dependent manner." (PMID 25426117, 2014). "Because the clinical significance of erythropoietin receptor (EPOR) signaling in human non-small cell lung cancer (NSCLC) also remains controversial, our aim was to study whether EPO treatment modifies tumor growth and if EPOR expression has an impact on the clinical behavior of this malignancy." (PMID 24155958, 2013). "Thus further investigation into this, and correlating the tumor hypoxic status to EPO/EPOR expression may be warranted." (PMID 24004818, 2013). "However, the functional role of EPO in tumor biology is still far from being fully understood." (PMID 23052842, 2013). "We compared the effects of EPO and SPO on tumor cell viability across eight human cancer cell lines." (PMID 41598205, 2025). "EPO signaling induces TAM immunomodulation through NRF2-mediated heme depletion, resulting in compromised anti-tumor T cell immunity." (PMID 41417432, 2025).
tumor (continued). "This suggests that pseudohypoxia, along with the tumor microenvironment and the effects of HIF1A activation, leads to increased expression of hypoxia-related genes such as EPO." (PMID 40332447, 2025). "Based on this clinical course, it is more likely that local tumor control through WBRT for metastatic brain lesions contributed to the improvement in erythrocytosis and elevated serum EPO levels." (PMID 40502212, 2025). "When VHL-induced degradation is impaired, HIF1A and HIF2A accumulate, resulting in elevated levels of erythropoietin (EPO), vascular endothelial growth factor (VEGF), and other growth factors, which promote tumor growth." (PMID 40005423, 2025). "One of the key components regulated through EPO signaling is vascular endothelial growth factor (VEGF), which acts as a growth factor for endothelial cells within the tumor microenvironment." (PMID 41375075, 2025). "Overall, these data support the computational prediction that NOS2 (iNOS) serves as a shared molecular target of both EPO and SPO and demonstrate that both extracts can downregulate iNOS transcription and NO production in inflammatory and tumor cell contexts." (PMID 41598205, 2025). "We analyzed the tumor and surrounding healthy tissue from patients with ccRCC after radical nephrectomy to explore hypoxia-related HIF1A and EPO expression and JAK2/STAT5 signaling pathways." (PMID 40332447, 2025). "Based on our results from the tumor and surrounding healthy tissue samples, HIF1A emerged as the primary determinant of EPO, EPOR and JAK2/STAT5A signaling pathway expression in ccRCC." (PMID 40332447, 2025). "A significant increase in UCK2, HMMR, and MAGEA6 expression and a significant decrease in CXCL8, EPO, PPARGC1A, FTCD, and CFHR3 expression was observed in tumor tissues." (PMID 38694506, 2024). "This includes genes involved in anaerobic energy metabolism (e.g. GLUT1), regulating oxygen transportation (e.g. EPO), and initiating angiogenesis (e.g. VEGF), resulting in a higher probability of the formation of neoplasms and subsequent tumor formation." (PMID 37883464, 2024). "While some studies have suggested that EPO and EPOR promote tumorigenesis in adult and pediatric cancers, others have suggested their tumor-suppressive roles." (PMID 38542288, 2024). "EPO stimulation through these receptors leads to increased VEGF expression, promoting angiogenesis and tumor growth." (PMID 38542288, 2024). "These activated fibroblasts become hubs for generating PDGF-CC, EPO, and FGF, collectively promoting VEGF-independent tumor angiogenesis." (PMID 38542288, 2024). "HIF1 activates more than 100 downstream genes, commonly including vascular endothelial growth factor (VEGF), erythropoietin (EPO), GLUT1, and LDHA, regulating important biological processes required for tumor survival and development." (PMID 38715141, 2024). "Among these, HIF-1α primarily regulates anaerobic glycolysis and cell survival, while HIF-2α regulates erythropoietin (EPO) and tumor stemness or pluripotency." (PMID 39199143, 2024). "However, they might not develop from CD45+EPCs as tumor-associated CD45+EPCs rarely develop to nucleate red cells under the induction of erythropoietin, especially those from the TME." (PMID 37649603, 2023). "The tumor expressions of GLUT-1, Cyclin D1, TGF-α, VEGF, and EPO are specific targets of HIF-2a in chronic hypoxia when an oxidative phenotype is induced and even when tumor aggressivity and treatment resistance are high." (PMID 36294785, 2022). "Knockdown of MT1X in the setting of hypoxia reduces the accumulation of HIF-1α, EPO, VEGF, and CA9, which are important factors that regulate tumor cell adaptation to hypoxia (P<0.05)." (PMID 36149322, 2022).
tumor (continued). "Except for EPO and GP1BA, the other 9 genes showed significant differences in their expressions between HCC and non-tumor tissues in TCGA cohort." (PMID 35739471, 2022). "Tumor cells in the hypoxic niche not only produce cytokines including IL-6, IL-10 and TGF-β, but also upregulate pro-angiogenic factors (VEGF, PDGF-β or EPO) that recruit pericytes and trigger neoangiogenesis." (PMID 35769460, 2022). "Tumor lysates were subjected to ELISA, which revealed significantly decreased expression of VEGFA, EPO, SDF-1α, and SCF protein in tumor lysates from mice treated with 32-134D (P < 0.05)." (PMID 35499076, 2022). "Analysis of the five hypoxia- and immune-related genes also showed high expression of EPO, TGFB1, TGFA, and PLAUR, but low expression of TEK in tumor samples." (PMID 35222525, 2022). "Delivery of oxygen and continued proliferation of the tumor can be achieved by angiogenesis, promoted by downstream products of hypoxia-inducible factor (HIF), such as VEGF, PDGF, and EPO." (PMID 33192500, 2020). "In turn, HIF-1α is conducive to the adjustment of tumors to hypoxia through transcriptional activation of more than 100 downstream genes including LEP, EPO, PKM, etc.; in this regard, HIF-1α further promotes the proliferation of tumor cells." (PMID 33681184, 2020). "Under hypoxic conditions, tumor cells induce HIFs (the activated form of HIF) to promote synthesis and expression of pro-angiogenic factors, such as VEGF and EPO (erythropoietin)." (PMID 31121863, 2019). "The mammary gland tumor sections from rats treated with EPO-TAMNLC were generally characterized by massive degenerative and with necrotic tissues and markedly reduced number of tumor cells." (PMID 31291309, 2019). "HIF1α activates the transcription of dozens of genes including erythropoietin (EPO), which provide tumor cells with the device to maintain vigorous growth and expansion in a hypoxic microenvironment." (PMID 31752873, 2019). "Immunohistochemistry results confirmed the truncated IRP1 and overexpressed HIF-2α, EPO and EPOR in tumor cells." (PMID 29534684, 2018). "We decided to assess the impact of the simultaneous use of erythropoietin (Epo) and LFM-A13 on signal transduction in colon DLD-1 and HT-29 cells, as well as in tumor xenografts." (PMID 29690619, 2018). "This analysis indicated that in the tumor region, which had a higher level of HIF-1α, EPO and EPOR also expressed higher and cells grew faster." (PMID 29238266, 2017). "It cannot be ignored that our data of protein expression of EPO and EPOR comes from tumor tissue and normal adjacent tissue." (PMID 29238266, 2017). "Self-sustainable EPO/EPOR signaling was a mediator of hypoxia induced cell growth in dual EPO and EPOR-positive NSCLC tumor." (PMID 29137269, 2017). "Bortezomib, a proteasome inhibitor, is reported to inhibit tumor adaptation to hypoxia via blocking of hypoxic activation of HIF-1 and induction of its target genes, including VEGF and erythropoietin (EPO)." (PMID 28841148, 2017). "With primary tumor cell culture and patient-derived tumor xenograft (PDX) mouse model, the EPO secretion from the tumors of these 14 patients was verified." (PMID 29137269, 2017). "Furthermore, EPO also leads to increased expression of anti-apoptotic proteins such as bcl-2 and bcl-XL and their activation is likely to account, at least in part, for the enhanced anti-tumour effect of anthracycline-based chemotherapy which accompanies a pCR." (PMID 29108271, 2017). "The serum EPO in 14 of 35 enrolled NSCLC patients were found elevated significantly and decreased to normal level after tumor resection." (PMID 29137269, 2017). "That means in the tumor region, which had a higher HIF-1α level, EPO also expressed higher and cells grew faster." (PMID 29238266, 2017).
tumor (continued). "Mann–Whitney non-parametric U test confirmed the significant differences in tumor vessels VEGF expression in both control (p < 0.001) and erythropoietin-treated DLD-1 xenografts compared with Ht-29 xenografts (p < 0.001)." (PMID 27543111, 2016). "Originally, the stimulating effect of erythropoietin on HNSCC has been assumed to involve angiogenesis and tumour hypoxia." (PMID 25182342, 2014). "Despite the fact that many tumor cells were confirmed to possess the EPOR, there is still some debate on stimulatory effects of EPO on these cells." (PMID 25426117, 2014). "EPO gene expression correlated with shortened relapse-free survival and pharmacologic JAK2 inhibition revealed a synergistic effect with chemotherapy in tumor growth inhibition in vivo." (PMID 25426117, 2014). "Because of adverse tumor response and/or poorer survival in ESA-treated cancer patients, studies of EPO effects on cancer stem cells was initiated." (PMID 25426117, 2014). "Tumor cells turn on the hypoxia-inducible transcription factor oxygen-sensing system and regulate the downstream genes, such as VEGF, iNOS, EPO, GLUT1, and GLUT3, to adapt to hypoxia and increase tissue oxygenation." (PMID 25310823, 2014). "While the hypoxic microenvironment plays a critical role in the development and progression of tumours in general, it is of special significance in the case of RCC because of the link between VHL, HIF and EPO." (PMID 23305401, 2013). "Numerous strategies are currently under investigation to directly target tumour hypoxia, including the hypoxia cytotoxin tirapazamine, HIF-1 targeted agents, gene therapy, and increasing oxygenation using erythropoietin." (PMID 22333602, 2012). "The protein products of induced by this pathway (e.g. EPO, VEGF, several glycolytic enzymes) allow clones of tumour cells to gain growth advantage under unfavourable conditions, and this concept is pivotal in switching to a more malignant phenotype." (PMID 15341671, 2004). "The authors conducted a large set of in vitro and in vivo experimental investigations, making an important contribution to the EPO-cancer field; they suggested that EPO can promote an immunosuppressive, non-inflamed tumor microenvironment (TME)." (PMID 41375075, 2025). "In our cases, hematologic normalization occurred promptly after tumor removal regardless of preoperative EPO concentrations, indicating that serum EPO has limited clinical utility beyond its diagnostic contribution." (PMID 41487860, 2025). "Despite the large tumor size, both patients showed only upper-normal serum EPO concentrations, suggesting that tumor weight does not necessarily correlate with EPO secretion." (PMID 41487860, 2025). "Tumorigenic effects of EPO, independent of any direct impact on tumor cells, have also been reported." (PMID 41375075, 2025). "A clinical trial in head and neck cancer patients showed that EPO administration led to tumor growth and did not improve overall survival or progression-free survival." (PMID 40688089, 2025). "However, a decrease of tumor size and downregulation of the HIF-2α specific genes PAI-1, CCND1, EPO, and GLUT-1 have been reported in ccRCC xenografts treated with PT-2385 (aka MK-3795), a new HIF-2α inhibitor." (PMID 40227577, 2025). "Our histological observations are consistent with an epithelial cell of origin of the EPO-GEMM tumors, which was confirmed by generating tumors with comparable latency and presentation in a CK8-CreERT2; LSL-Cas9 host that restricts tumor initiation to the CK8+ epithelial compartment." (PMID 38177458, 2024). "In hypoxic tumor environments, FOXO4 downregulates hypoxia-inducible factor 1α (HIF-1α), thereby suppressing responses to hypoxia such as the expression of glucose transporter type 1 (GLUT-1), erythropoietin (EPO), and vascular endothelial growth factor." (PMID 39085238, 2024).